NF2 (NF2, moesin-ezrin-radixin like (MERLIN) tumor suppressor)
Diseases named in the same sentence as NF2 in open-access papers (continued):
Sharing a sentence is not in itself a finding about the gene and the disease.
meningioma (continued). "Early research has demonstrated that it may be an effective treatment of NF2 deficient meningioma, however further investigation is required." (PMID 37860270, 2023). "Meningioma in this circumstance are described as NF2 associated Meningioma." (PMID 37860270, 2023). "NF2-mutated meningiomas show high chromosome instability during progression." (PMID 36230612, 2022). "According to the 2021 WHO brain tumor classification scheme, convexity and the majority of spinal meningiomas have similar molecular findings (loss of chromosome 22q and/or NF2 mutations), while skull base meningiomas demonstrate different mutations (AKT1, TRAF7, SMO, and PIK3CA)." (PMID 36179256, 2022). "All our 3 cases of multiple meningiomas belonged to the NF2 mutation group." (PMID 36267986, 2022). "PTPRJ promotes cell adhesion and inhibits PDGFR signaling, and its loss may promote meningioma progression through interacting with NF2 loss." (PMID 35706047, 2022). "Interestingly, different mechanisms play a role between BI and bone invasion in some meningioma subtypes, depending on tumor location and genomic features and, among them, NF-2 and TRAF7 mutations." (PMID 36077700, 2022). "Recent reports have speculated structure variants such as multiple CNVs, especially 1p loss, as an epigenetic “second-hit” following NF2 alteration for aggressive-type meningiomas." (PMID 35570314, 2022). "NF2-deficiency is the most prominent mutation in meningioma." (PMID 35216092, 2022). "However, gaining of additional molecular features of high-grade meningioma, such as 22q/NF2 loss, chromosome instability, and homozygous CDKN2A/B deletions leads to tumor progression." (PMID 35440040, 2022). "“NF2 meningioma” was defined as meningiomas with presence of NF2 mutation and/or 22q loss." (PMID 35570314, 2022). "They speculated that the inactivation of NF2 in meningiomas may be more likely to cause ferroptosis." (PMID 35530363, 2022). "The most common driver mutation is biallelic loss of NF2, accounting for > 50% of meningiomas." (PMID 34846640, 2022). "In univariate analyses, statistical associations were identified between worse prognosis and NF2 meningioma (HR:1.9, confidence interval [CI] 1.01–3.58, p = 0.04), STR (HR: 4.51, CI 2.46–8.25, p = 1.0 × 10–6), and Ki-67 index ≥ 4 (HR: 4.91, CI 2.7–8.95, p = 1.8 × 10–8)." (PMID 35570314, 2022). "Furthermore, we show that monoclonal formation can be observed in both NF2-loss and non-NF2 mutant tumors and those meningiomas can undergo branched evolution to display intertumoral heterogeneity in the same patient." (PMID 35568945, 2022). "The tumor suppressor gene NF2 encodes the protein merlin (or schwannomin), which is correlated with the onset of schwannomas and meningiomas in the familial syndrome neurofibromatosis 2 and is found in >50% of sporadic meningiomas." (PMID 35565385, 2022). "Among the non-NF2 mutant meningioma subgroup, mutations in SMO and SUFU were identified." (PMID 36010600, 2022). "NF2 mutations and the loss of chromosome 22 are frequently observed in these meningiomas." (PMID 35712491, 2022). "One NF2 wild type meningioma (28M) had PDGFRB and RAD50 mutations." (PMID 35049691, 2022). "TERT mutations occurred more frequently in NF2 wild-type meningiomas." (PMID 35299730, 2022). "For example, Neurofibromatosis type 2 (NF2) is the first mutation identified in meningioma, which could be found in almost 50% of sporadic meningiomas." (PMID 36538194, 2022). "In 17% of the meningiomas, epigenetic NF2 inactivation was the only cause of NF2 deficiency." (PMID 36267986, 2022). "Thus, evaluation of CNV status in NF2 mutated meningiomas depending on anatomical location is also needed in the future." (PMID 35570314, 2022). "Another NF2-mutated meningioma featured SMARCB1 R386H and BRIP2 mutations." (PMID 35049691, 2022). "Meningiomas can be classified into neurofibromatosis type 2 (NF2) mutated and non-NF2 mutated." (PMID 35892898, 2022).
meningioma (continued). "Radiation-induced meningiomas were associated with structural rearrangements of the NF2 gene, loss of chromosomes 1p and 22q, and decreased focal gene mutations that are characteristic of non-NF2 tumors." (PMID 35712492, 2022). "The highest TMB (TMB: 5.13 muts/Mb) was found in the NF2/SMARCB1-mutated meningioma (24M)." (PMID 35049691, 2022). "In this study, many of the meningiomas with NF2 alteration/22q loss displayed bone invasion, suggesting that meningiomas with bone invasion could harbor NF2 variants preoperatively." (PMID 35804955, 2022). "Also, in recent years, several classifications based on integrated molecular analyses have been proposed and have indicated that the prognosis of patients with meningiomas with NF2 variant/22q loss ranges from good to poor." (PMID 35804955, 2022). "These efforts identified brigatinib (ALUNBRIG®), an FDA-approved inhibitor of multiple tyrosine kinases including ALK, to be a potent inhibitor of tumor growth in established NF2 deficient xenograft meningiomas and a genetically engineered murine model of spontaneous NF2 schwannomas." (PMID 34264955, 2021). "Notably, non-synonymous genetic variants of SMO and POLR2A were restricted to diploid meningiomas, whereas NF2 mutations were only found among tumors that showed -22/22q─ (with or without a complex karyotype)." (PMID 34868937, 2021). "Up to 80 different NF2 mutations have been previously reported in meningiomas." (PMID 34868937, 2021). "In addition to NF2, another gene located on chromosome 22q that can be altered is CHEK2, which has been described in NF2 mutated meningiomas." (PMID 34679551, 2021). "Furthermore, the NF2 mutations are preferentially located in meningiomas at the convexities, whilst skull base tumors harbor other mutations and hence driven by other genetic alterations." (PMID 33809258, 2021). "Altogether, these results suggest that presence of NF2 mutation in the context of an isolated monosomy 22/22q─ confer a low risk of recurrence for WHO grade 1 meningiomas, while complex karyotypes and isolated loss of chromosome 22 in the absence of NF2 mutation would confer a poorer prognosis." (PMID 34868937, 2021). "Indeed, NF2 overexpression is associated with neurofibromatosis type 2, an inherited genetic disease involving meningioma." (PMID 33622177, 2021). "NF2 mutations, common in other meningiomas, are rare in this subtype." (PMID 33319313, 2021). "Interestingly, analysis of EZH2, the catalytic subunit of the PRC2 complex which acts to antagonize the SWI/SNF complex, indicated an increased expression in clear cell meningiomas compared to meningiomas with NF2 mutation (adjusted p = 1.70e-07; Suppl." (PMID 33319313, 2021). "Frequent NF2 mutations were observed in this series of atypical meningiomas across both groups, yet more prominent in Group I. Previous studies reported that NF2 was mutated in about half of the cases, whilst the present study found that 55% of the samples were mutated." (PMID 33809258, 2021). "Of the non-NF-2 gene alterations associated with meningiomas, TRAF7 is the most common." (PMID 34638590, 2021). "While the surprisingly high number of mutations per sample might be explained by radiation exposure which is a known risk factor for this secondary lesion, most primary pediatric meningiomas are NF2 associated." (PMID 34337412, 2021). "In an initial attempt, we wondered whether recurrent somatic mutations reported to occur in adult meningiomas exclusive of NF2 alterations are present in pediatric meningiomas as well." (PMID 34495383, 2021).
meningioma (continued). "OGN has been implicated in meningioma through effects on mTOR and NF2 signaling, but whether it may be a therapeutic target is unclear." (PMID 33622177, 2021). "KLF4 mutations are present in ~50% of non NF2 mutated tumors and in up to 9–12% of all meningiomas." (PMID 33801089, 2021). "Conversely, atypical and anaplastic meningiomas are disproportionately associated with NF-2 mutations and/or 22q chromosome deletions, which may relate to genetic factors associated with a mesodermal origin." (PMID 34638590, 2021). "Loss of NF2 or instability of chromosome 22 is a frequent feature of sporadic meningiomas as well." (PMID 34885143, 2021). "Deletions, nonsense mutations, splice site mutations, and translocations in NF2/Merlin are identified in 50–60% of the general population of patients with meningiomas, and loss of chromosome 22 in tumor tissue can be seen in 40–80% of patients developing meningioma." (PMID 33445724, 2021). "Importantly, the majority of meningiomas with NF2 mutations demonstrate chromosomal instability and increased risk of tumor progression into high-grade meningiomas." (PMID 33611710, 2021). "The results suggest that the inciting event for many high-grade meningiomas is a copy number loss of chromosome 22, which in addition to containing the tumor suppressor gene NF-2 may also contain other tumor suppressor genes such as SMARCB1, CHEK2, and CLH22." (PMID 34638590, 2021). "Overall, WHO grade 1 meningiomas harbored numerous and heterogeneous genetic variants, which most frequently affected the NF2 (47%) gene and to a less extent the PNMA6A (22%), TIGD1 (16%), SMO (13%), PTEN (13%), CREG2 (9%), EEF1A1 (6%), POLR2A (6%), ARID1B (3%), and FAIM3 (3%) genes." (PMID 34868937, 2021). "The mutational spectrum of atypical meningiomas is mainly characterized by NF2 mutations that co-occur with genomic instability or recurrent SMARCB1 mutations in primary atypical meningiomas, and with TERT promoter mutations in secondary (i.e., arisen from the progression of benign tumors) ones." (PMID 33670055, 2021). "The associated risk of meningiomas in NF2 corresponds to the type and location of mutations within the gene, with a greater risk associated with truncating mutations than nontruncating mutations and with mutations occurring toward the 5′ end of the gene than the 3′ end of the gene." (PMID 33801089, 2021). "Loss of heterozygosity (LOH) and inactivating NF2 mutations are found in 40–80%, supporting a classical two-hit hypothesis for meningioma development." (PMID 34495383, 2021). "Regarding patients harboring NF2 mutations and/or 22q loss, these mutations were more frequent in meningiomas of neural crest than in those of paraxial mesodermal origin (p = 3.9 × 10–12) and more frequent in those of neural crest rather than dorsal mesodermal origin (p = 5.0 × 10–5)." (PMID 33772057, 2021). "It was used to demonstrate that overexpression of PDGF (platelet-derived growth factor), in meningiomas in arachnoïdal cells could induce meningiomas independently of Nf2 mutation." (PMID 34359639, 2021). "In addition to the downstream effects of germline mutations to NF2, it is worth mentioning that a number of sporadic mutations have been implicated in the pathogenesis of meningioma." (PMID 33445724, 2021). "While approximately 40% of young patients presenting with a solitary meningioma have an underlying germline NF2 mutation, the diagnosis can be difficult to ascertain genetically due to mosaic status and may require years to confirm clinically." (PMID 34495383, 2021). "A different embryologic origin could explain why the non-NF-2 associated meningiomas are almost always benign, heavily favor meningothelial histology, and do not experience the multiple chromosomal aberrations that are common with the majority of NF-2 tumors." (PMID 34638590, 2021). "However, meningiomas with NF2 mutations or 22q loss were significantly associated with neural crest and dorsal mesoderm origin." (PMID 33772057, 2021).
meningioma (continued). "NF2 is the most common and well-known familial syndrome associated with meningioma risk." (PMID 33801089, 2021). "A small cohort uncovered NF2 gene fusion is strongly associated with meningioma progression, however, a comprehensive landscape of gene fusions in meningioma and whether subtypes of meningiomas had distinct gene fusions features were still unclear." (PMID 33807688, 2021). "Around 40% of sporadic meningiomas lack NF2 mutations and driven by other genetic aberrations." (PMID 33801089, 2021). "However, meningiomas with NF2-associated mutations were significantly associated with neural crest origin (p = 3.9 × 10–12)." (PMID 33772057, 2021). "In NF2 wild-type meningiomas, mutations in TRAF7, KLF4, AKT1, and SMO were noted." (PMID 34778063, 2021). "Meningiomas can also be genetically determined and are present in several genetic syndromes such as: neurofibromatosis type 2 (NF2), which is most frequently associated with meningiomas, Gorlin, Li Fraumeni, Cowden, von Hippel–Lindau, and multiple endocrine neoplasia type 1 (MEN1)." (PMID 34679551, 2021). "Indeed, we would not have anticipated a drug known for its ability to inhibit ALK demonstrating preclinical efficacy in either NF2 associated schwannoma or meningioma." (PMID 34264955, 2021). "The main genetic alteration in meningioma is the deletion of genes on chromosome 22q, in particular, loss-of-function mutations in the neurofibromin 2/merlin/schwannomin (NF2) gene, dividing meningiomas into NF2-mutant (60%) and wild-type groups." (PMID 33611710, 2021). "NF2 (neurofibromatosis 2) is the most common mutation in meningiomas, occurring in 40–60% of sporadic meningiomas, and has been implicated as a driver of meningioma tumorigenesis." (PMID 34300316, 2021). "By age 70, the cumulative incidence of meningioma is 80% in patients with proven NF2 mutations." (PMID 33445724, 2021). "NF2 is most commonly associated with the development of bilateral vestibular schwannomas; however, patients also have a predisposition to development of other tumors including meningiomas, ependymomas, and peripheral, spinal, and cranial nerve schwannomas." (PMID 31161239, 2020). "Furthermore, H3K27me3-negative meningiomas were associated with DNA methylation patterns observed in more aggressive meningiomas, and there was a proportionally higher percentage of NF2 mutations among H3K27me3-negative meningiomas." (PMID 33330036, 2020). "The mutation in the NF2 gene is the most common genetic cause of meningioma." (PMID 32742192, 2020). "Patients that present with multiple meningiomas exhibit different NF2 mutations in respective tumors while identical biallelic NF2 mutations in patients with multiple tumors have been demonstrated, indicating that tumors can arise independently or through mosaicism or clonal spread." (PMID 33346248, 2020). "NF2-associated meningiomas may be of any histologic subtype, but are most often of the fibrous variant." (PMID 31161239, 2020). "Our comparison of the volume and the growth rate of NF2-associated spinal and cranial meningiomas point to the differences in timing of tumor initiation and/or to the differences in tumor progression (e.g., non-linear, saltatory growth) at these two anatomical locations." (PMID 32724039, 2020). "In this study, the presence of AKT1 and SMO mutations along with mutated MYBL2, both in the NF2-mutant primary atypical meningioma tumor and the derived cell line, proved that the meningioma-derived primary cell line had retained the genetic signature of the original tumor." (PMID 32742192, 2020). "Knowing that NF2 mutations are the most common single gene mutation in meningioma and that multiple meningiomas arise in half of the patients with the NF2 syndrome, it is most likely that the NF2 mutations are the initiating event for the aggressive tumors from ED group #2." (PMID 31963394, 2020). "Meningiomas with NF2 mutations have a proclivity for the cerebral hemispheres." (PMID 33330036, 2020).
meningioma (continued). "NF2-associated ependymomas more often arise in patients with truncating NF2 mutations, suggesting that ependymomas are associated with more aggressive variants of the syndrome, as with meningiomas." (PMID 31161239, 2020). "In this study, for patients with unilateral vestibular schwannoma or multiple meningiomas, diagnosis of an ependymoma carried the highest positive predictive value for the diagnosis of NF2 of any lesion, with confirmed pathogenic mutations in up to 68% of patients." (PMID 31161239, 2020). "We showed that AKT1 E17K-mutated meningiomas have a less immunosuppressive tumour microenvironment when compared to grade I NF2 meningiomas; this may explain why some NF2 tumours have high progression/recurrence rates." (PMID 32070062, 2020). "Similarly, NF2-deficient human meningioma cells and NF2-KD arachnoidal cells show rapamycin-sensitive constitutive mTORC1 activation." (PMID 32968052, 2020). "Screening for additional targets suggested that co-inhibition of EPHA2 may further reduce proliferation of NF2-associated meningiomas in combination with mTORC1/2 inhibition, though this finding requires further clinical validation." (PMID 31161239, 2020). "VS in NF2 patients is diagnosed much earlier than in sporadic cases due to autosomal dominant inheritance, which leads to screening of known patients and the presence of other symptoms causing brain tumors such as meningiomas, astrocytomas and ependymomas." (PMID 32244314, 2020). "In addition, the meningiomas of 23 patients showed SUFU mutations, 18 in NF2-mutant (3.7%) and 5 in NF2-wt meningiomas (1.3%, p = 0.033)." (PMID 33087175, 2020). "NF2 mutations are found in both sporadic meningiomas, with a predilection for the fibrous and transitional variants preferentially located at the convexity, and in the meningiomas occurring as part of the NF2 syndrome." (PMID 31963394, 2020). "Additionally, it has been found that tumors initially diagnosed as WHO grade II meningiomas commonly have loss of NF2 with alterations in SMARCB1 and have an increased H3K27 methylation." (PMID 32982948, 2020). "One study found in primary, non-NF2 mutated meningiomas, the pro-tumor inflammatory mediator IL-1β induced methylation of the NF2 promotor through various mediators that could act as novel targets." (PMID 32982948, 2020). "Interestingly, such mutations were found to be associated with tumorigenesis and progression of NF2 independent meningiomas." (PMID 32742192, 2020). "NF2 is a tumor suppressor gene that is located on the long arm of chromosome 22q12, and was the first single-gene mutation to be linked with risk of developing meningioma." (PMID 31191822, 2019). "NF2 was affected in 44% of our tumor samples (n = 8/18) by frameshift mutations (n = 4/18), stop-gain mutations (n = 3/18) and splicing error (n = 1/18), which is in accordance with the literature as the primary inactivated tumor suppressor in meningiomas." (PMID 31470906, 2019). "NF2 mutant meningiomas were associated with larger tumor size (8-fold increase), presence of vasogenic edema, and higher mitotic proliferation on univariate and independently on multivariate regression (p’s < 0.05) after controlling for preoperative and tumor features." (PMID 31191822, 2019). "Familial meningiomas are related to various mutations in the NF2 gene." (PMID 31477146, 2019). "Merlin/NF2 loss is a key driver in the development of both syndromic and most sporadic meningiomas." (PMID 31652973, 2019). "Interestingly, 7 out of 8 female patients (87%) harbored NF2 mutations which is in line with the largest dataset available which reported on 112 NF2-mutated meningiomas including 79 female patients corresponding to a female preponderance of approximately 70%." (PMID 31470906, 2019).